CD4 (CD4 molecule)
Diseases named in the same sentence as CD4 in open-access papers (continued):
Sharing a sentence is not in itself a finding about the gene and the disease.
viral infection (continued). "CD4+ T cells usually function as helper cells but have been shown to be capable of cytotoxicity after several virus infections, including those with coronaviruses." (PMID 32948688, 2020). "Particularly, during the CD4 T cell response to acute viral infection, EZH2 spikes within 3 days after infection and declines to a basal level comparable to that in the naive state at day 8 postinfection." (PMID 32999031, 2020). "All the patients in our study had no history of immunodeficiency before admission, so decreased CD4+ T cells count was regarded as a subsequent change of viral infection." (PMID 33537328, 2020). "We also know that CD4 T cells are crucial for orchestrating a number of immune responses to viral infection." (PMID 32462053, 2020). "Activated CD4+ T cells are indispensable for the effector function during acute viral infections and for the expansion of CD8+ T cells." (PMID 33391280, 2020). "In response to acute viral infection, virus-specific CD4 T cells differentiate into either TFH or TH1 cells (16, –, 18)." (PMID 32999031, 2020). "We further investigated the effects of the presence of high levels of activated vs. naive CD4+ T cells specific for a viral determinant at the time of viral infection on the development of demyelinating disease." (PMID 33086489, 2020). "In many viral infections, CD4+ and CD8+ T cells are key for control and clearance of an acute infection." (PMID 33010815, 2020). "Blocking of other receptors which facilitate trans-infection of HIV, such as DCIR, have also shown efficacy in decreasing viral infection of CD4+T cells." (PMID 32582566, 2020). "Currently, most vaccine designs of the virus focus on the NAb production elicited by the S protein, but T cell-mediated immunity (both CD8+ and CD4+ helper cells) against the viral infection deserves more attention." (PMID 32635180, 2020). "Taken together, the data indicated that EZH2 acts as an indispensable regulator to preserve metabolic fitness by coordinating mitochondrial respiration, glycolysis, and fatty acid synthesis in CD4 T cells during acute viral infection." (PMID 32999031, 2020). "Activated CD4+ T cells during viral infections differentiate into subsets of T cell helper effector cells." (PMID 33425136, 2020). "Collectively, these data demonstrated that an abundance of EZH2 protein accelerates early-activated CD4 T cell expansion in acute viral infection." (PMID 32999031, 2020). "Recently, Lodge found that CD4 is the direct target of miR-222 through luciferase assays and reported that the ectopic expression of miR-222 mimics in human macrophages reduced both CD4 mRNA and cell surface CD4, which resulted in virus infection." (PMID 31842954, 2019). "The CD4+IL-4+ cytokine response following KOS virus infection was elevated on day 14 PI, compared to D22 (ICP22 null) virus infection (21.6% vs. 6.9%, P < 0.001), but differences between these groups were not significant on day 28 PI (3.9% vs. 10%, P > 0.05)." (PMID 31387116, 2019). "In viral infection, a skewed immune response triggered by CD4+ cells via upregulation of IL-12 cytokine through stimulation by CTL was observed in the common carp." (PMID 30616664, 2019). "Cell-to-cell transfer of HIV-1, or trans infection, is a highly efficient mechanism of virus infection of CD4+ T cells by professional antigen-presenting cells (APCs), that is, dendritic cells (DCs), macrophages, and B lymphocytes." (PMID 31304185, 2019). "Much recent research on IFITM proteins has focused on their role in cellular resistance to viral infections, but their function in CD4+ T cells during the adaptive immune response is less well understood." (PMID 30365177, 2019). "Viral infections are considered to elicit NAbs, CD4 T cell responses, and cytotoxic CD8 responses at the same time as part of the crucial host defense mechanism." (PMID 31338384, 2019).
viral infection (continued). "This also provided an opportunity to examine the generation of CD4+ T-lymphocytes in the lungs specific to the same P25 epitope as in M. tuberculosis, but in a different inflammatory context of acute viral infection." (PMID 30899256, 2019). "The majority of antigen-specific CD4 T cells differentiate into T helper type 1 (Th1) and follicular helper T (Tfh) cells following viral infections and provide help to CD8 T cells and B cells." (PMID 31552052, 2019). "Compared with acute viral infection, virus-specific CD4+ T cells in LCMV clone 13 persistent infection model exhibit deficiency in production of Th1-type effector cytokines and fail to function optimally following viral re-challenge." (PMID 30828337, 2019). "Propelled by the antagonism of Bcl6 and Blimp-1, activated CD4+ T cells undergo a bimodal fate decision during acute viral infection: becoming either Tfh (Bcl6+Blimp1−) cells or Th1 (Bcl6−Blimp1+) cells." (PMID 30828337, 2019). "In the context of viral infections, both CD4 and CD8 T cells play important roles in controlling and clearing the pathogen." (PMID 31382545, 2019). "It has, however, become clear that specialized CD4+ T-cell effector subsets with direct cytolytic capacity can be induced to target a number of viral infections, e.g. HIV, poliovirus and influenza in a granzyme B, perforin or FasL mediated manner." (PMID 31575882, 2019). "Little is known of the clonal composition or functional diversity within individual epitope-specific populations or how virus-specific CD4+ T cell responses evolve from primary to persistent viral infection." (PMID 31308093, 2019). "Although these responses were cytotoxic, they also exhibited a “helper” effect by promoting viral infection of CD4 T cells via interaction with dendritic cells." (PMID 31398241, 2019). "Here we discuss potential functions of CD4 CTLs in the late stage of aging in terms of protective roles against tumor development and viral infections." (PMID 31719197, 2019). "CD8+ and CD4+ T cells have been shown to contribute to IFN-γ expression during a number of viral infections." (PMID 30823555, 2019). "Most of the virus-specific effector CD4+ T cells will die and only a small portion of them will survive and further differentiate into memory T cells after the elimination of a viral infection." (PMID 30828337, 2019). "In PVM, lung CD4+ T cells constitutively express IL-21, and the number of IL-21+ CD4+ T cells increases following viral infection." (PMID 30969166, 2019). "Overall, our results indicate that memory CD4 T cell-derived IL-2 acts as a potent adjuvant in the lung that enhances the production of a broad early inflammatory response during acute viral infection." (PMID 31412088, 2019). "This study demonstrates that the IFITM family of proteins should be viewed not only as essential proteins for cellular resistance to viral infection but also as important regulators of CD4+ Th cell differentiation and function." (PMID 30365177, 2019). "In fact, following ICP22 null virus infection, CD4+perforin+ and CD8+perforin+ expression levels were similar to those following KOS virus infection at all time points measured." (PMID 31387116, 2019). "In immunocompromised transplant recipients, long-term control of viral infection and reactivation relies on the recovery and reconstitution of antiviral CD4+ and CD8+ T cells." (PMID 30897843, 2019). "The peak of CD4+IL-2+ responses following KOS infection on day 14 PI was greater than responses to D22 (ICP22 null) virus infection (79.4% vs. 64.5%, P < 0.01) and was reduced on day 28 PI (60.5% vs. 36.2%, P < 0.001)." (PMID 31387116, 2019). "After virus infection, immature CD4+ T cells proliferate and produce heterogeneous cell subsets, which play unique roles in the immune response." (PMID 31757053, 2019).
viral infection (continued). "Using mouse models of bacterial and viral infections, we showed that IL-3–secreting CD4+ T cells were generated by infection at the skin and mucosa but not by infections introduced directly into the blood." (PMID 31356170, 2019). "Efficient long-term control of persistent viral infection requires the coordinated action of Ag-specific CD4+ and CD8+ T cells." (PMID 31308093, 2019). "Similar CD4 T-helper support functions have been reported in viral infections or anti-viral vaccination." (PMID 31333674, 2019). "We considered the possibility that the distinct CD4+ T cell responses to tumors versus infection resulted from differences in the kinetics of antigen exposure: transient during acute viral infection versus persistent exposure to tumor antigens." (PMID 31801070, 2019). "In vivo, CD4-CTLs have been predominantly reported in humans in the context of persistent viral infections, including CMV and HIV, and various cancers." (PMID 31308093, 2019). "We know far less about how chronic viral infections affect CD4+ T cell responses than we do about CD8+ T cell exhaustion." (PMID 30828337, 2019). "Next, to determine if the inflammatory signature was dependent on viral infection, anti-CD4 or anti-CD81 receptor targeted neutralizing antibodies were applied to MDMs prior to HIV or HCV exposure and the treated cells were then tested for gene upregulation." (PMID 31260499, 2019). "The increase in the fraction of CD4+CD8+ double-positive T cells in the periphery has been discussed in terms of pathogenesis in autoimmune diseases or viral infection." (PMID 30626427, 2019). "Classically, human CD4-CTLs have been described in vivo almost exclusively in the setting of persistent viral infections, including CMV, dengue virus, and HIV." (PMID 31308093, 2019). "Allogeneic responses originally described in murine models highlighted these observations, and were further shown in human memory CD4+ T cell recall responses to persistent viral infections." (PMID 31440240, 2019). "GzmA-expressing CD4 CTL have been identified in several viral infections (HIV, CMV, vaccinia, DENV) and in rheumatoid arthritis." (PMID 31993061, 2019). "In dengue infection, one study showed that CD4+ T cells that produced either IFNγ or IL-2 correlated with protection from secondary virus infection in children." (PMID 30761131, 2019). "Activation of inflammasomes by viral factors triggers maturation of proinflammatory cytokines and chemokines that function to recruit immune cells, such as neutrophils, dendritic cells, inflammatory monocytes and CD4+ T cells, to the site of viral infection." (PMID 31367214, 2019). "Recent studies, including one in this issue, have shown the critical role of CD4 T cells in protection against viral infection." (PMID 30823555, 2019). "This review highlights the types of CD4+ T cells in fish and describes their direct role in cell-mediated and humoral immunity for protection against the intracellular bacterial as well as viral infections in fish." (PMID 30616664, 2019). "Overall, our data discloses the capacity of NKG2C+ adaptive NK cells to process and present HCMV antigens to memory CD4+ cytotoxic T cells, directly regulating their response to the viral infection." (PMID 31001281, 2019). "The role of CD4+ T cells in viral infections is evident, as they provide help to B cells for an enhanced antibody response, and CD4+ T cells help the generating cytotoxic and memory CD8+ T cells." (PMID 30626672, 2019). "A body of evidence indicates that cytotoxic CD4+ T cell mediated immunity is important for control of many viral infections, including HIV57–59." (PMID 30952887, 2019). "As the HIV-1 envelope protein, gp120 is critical for virus infection, because it is necessary for binding to specific cell surface receptors (CD4, CXCR4, and CCR5) on target cells and facilitating virus entry." (PMID 31379513, 2019).
viral infection (continued). "Upon viral infection, virus-specific CD4+T cells mainly differentiate into Th1 and Tfh (follicular helper T cell) cells, but not other helper subsets, such as Th2, Th17, and Th9 due to the strong type-I inflammation." (PMID 30828337, 2019). "CD4+ T cells are important in viral infections, since they provide help to B cells in enhanced antibody responses, and CD4+ T cells help CD8+ T cells in cytotoxic responses and memory differentiation." (PMID 30626672, 2019). "The most significant phenotype of CD4+ T cell response during chronic viral infection is a defect in Th1, while increasing in Tfh response." (PMID 30828337, 2019). "The present study examined the effect of resistance exercise on CD4+ T cell activation and utilized a viral model to indirectly assess intracellular metabolic activity via viral infection." (PMID 31552706, 2019). "CD4+ T cells also help in controlling viral infection through the secretion of cytokines that promote and maintain a strong antiviral CD8+ T cell response, and help in the generation of an effective B cell response." (PMID 30921340, 2019). "The second barrier to viral infection is the adaptive immunity, which is comprised of activated CD4+, CD8+ T cells and antibody-secreting plasma cells." (PMID 30635014, 2019). "TH1 CD4+ T cells are commonly generated as a result of both acute and persistent viral infection and can be critical for CD8+ T cell function; but in the case of persistent infections, this population can be lost over time." (PMID 31379821, 2019). "CD4 CTLs cells are long-lived and have been shown in many viral infections to be effective in the elimination of infected target cells." (PMID 31440240, 2019). "We verified these findings by examining an independent combination of markers – co-expression of CD38 and HLA on both CD4+ and CD8+ T cells is associated with T cell activation in the context of viral infection." (PMID 31368890, 2019). "In terms of adaptive immune cells, CD8+ T cell- and CD4+ T cell-mediated immune responses play a critical role in the control of viral infection." (PMID 30828337, 2019). "In vivo studies of acute viral infection showed accelerated expansion and recession of virus-specific CD4 + and CD8+T cells in Zfp36 KO animals." (PMID 29848443, 2018). "The use of varicella vaccine is recommended in varicella-susceptible adults, as long as they have a CD4+ count above 200 cells/μL; the same CD4+ threshold is used for MMR and yellow fever vaccines." (PMID 39449989, 2018). "During chronic viral infection, the inflammatory function of CD4 T-cells becomes gradually attenuated." (PMID 30487586, 2018). "This study demonstrated that deletion of CD2AP in T cells results in skewing of CD4 T cell differentiation towards TFH cells in response to viral infection, leading to enhanced control of LCMV that requires GC-derived high affinity antibody responses." (PMID 29734372, 2018). "This process mainly relies in the first HIV-1 Env-CD4 interaction and signaling, which are key for pore fusion formation and productive viral infection." (PMID 29636433, 2018). "Virus specific CD4 T-cells have an important role in controlling viral infections, not only by helping the CD8 T-cell cytotoxic activity and protective antibodies production by B cells, but also exercising antiviral functions." (PMID 30619267, 2018). "Collectively, our scRNA-seq analyses highlight that IL-10-producing CD4 T cells responding to chronic viral infection are comprised of multiple transcriptionally distinct subsets." (PMID 30487586, 2018). "CD4+ CTL have been identified mostly during viral infections, suggesting that one of the main roles of CD4+ CTLs is antiviral immunity." (PMID 30150988, 2018). "Functional characterization of the initial events of the viral infection showed that Envs from the LTNP-ECs were ineffective in the binding to CD4 and in the key triggering of actin/tubulin-cytoskeleton modifications compared to Envs from chronic patients." (PMID 29636433, 2018).
viral infection (continued). "Overall, our data reveal that ELCs are able to maintain low expression of several inhibitory receptors on CD4+ T cells, despite ongoing viral infection for a prolonged period of time." (PMID 29403500, 2018). "Upon delayed CD4 T cell depletion and brain infection with an acutely resolving viral infection, CD8 T cells also had aberrant bTRM development and required resupply from the vasculature." (PMID 30372487, 2018). "Applying adoptive transfers into Rag2-/- mice, we showed that CD4 T cells support CD8 T cells in controlling virus infection in the lungs." (PMID 30153311, 2018). "In line with this relative preservation from viral infection, CD4+ TCM cells are more preserved in SIV-infected SM compared to SIV-infected rhesus macaques." (PMID 29725327, 2018). "In peripheral blood, CD4+ T cells with low CD27, CD28, and CCR7 expression associate with viral infections and display cytotoxic functions." (PMID 30389931, 2018). "Other models of central nervous system (CNS) viral infection, however, suggest that CD4 T cell help is necessary for CD8 T cell function and CD8 bTRM development." (PMID 30372487, 2018). "These latent reservoirs are established early during acute viral infection and include, among others, macrophages and latently infected resting CD4+ T cells, these latently infected resting CD4+ T cells being the main viral reservoir." (PMID 29652795, 2018). "A large body of literature documents that the magnitude of the CD8 T cell response during persistent viral infections is regulated, in part, by IL-21 and IL-2 produced by CD4 T cells." (PMID 30372487, 2018). "To determine the contribution of T cell immune responses to cross-protection against A(H1N1)pdm09 virus infection, we used CD4 or CD8 specific antibodies to deplete T cells before and during A(H1N1)pdm09 challenge." (PMID 30356772, 2018). "CD4 T cell numbers were reduced in 72% of patients, and CD8 T cell and NK cell numbers were reduced in 27% of patients with severe virus infections and PIK3CD mutations." (PMID 29599765, 2018). "We use lymphocytic choriomeningitis virus (LCMV) to establish a mouse model of acute viral infection, in which virus - specific CD4+ T cells primarily differentiate into TFH and TH1 effector cells." (PMID 29875775, 2018). "In turn, this surrogate finding reflects an effective B and CD4+ T‐cell activation upon viral infection even under the influence of ONX 0914." (PMID 29295868, 2018). "To investigate the transcriptional heterogeneity of IL-10-producing CD4 T cells responding to chronic viral infection, we performed scRNA-seq on IL-10-expressing CD4 T cells from mice infected with persistent LCMV Cl13." (PMID 30487586, 2018). "In this context, in acute viral infection models, it has been demonstrated that the populations of virus specific CD4+ and CD8+ T cells primed for short periods of time, preferentially develop into memory T cells." (PMID 29946313, 2018). "Manipulating these variables in vaccination regimens in order to achieve a balance of CD4+ T cell effector differentiation appropriate for the respective context (e.g., viral infection or cancer) will be the next important challenge." (PMID 29951052, 2018). "The binding of HIV-1 glycans to L-selectin can be viewed similarly as viral rolling adhesion on CD4+ T cells to facilitate the binding to CD4 and other coreceptors, and thus to enhance viral infections." (PMID 30026537, 2018). "In this study, we investigated the effects of microvascular EC stimulation of resting CD4+ T cells in establishing viral infection and latency." (PMID 30285810, 2018). "This increase in infected TTM cells was mirrored by a decrease in the TCM numbers compared to the uninfected controls, suggesting that the viral infection resulted in the memory CD4+ T cells transitioning from TCM to TTM." (PMID 30026537, 2018). "Peripheral CD4/CD8 double-positive (DP) T cells are associated with autoimmune disorders, cancer, and viral infection." (PMID 30116750, 2018).